SGK1 (serum/glucocorticoid regulated kinase 1)
Diseases named in the same sentence as SGK1 in open-access papers (continued):
Sharing a sentence is not in itself a finding about the gene and the disease.
heart disease (5 papers, 2016 to 2023). "The encoding gene SCN5A, ENaC, and the mediator SGK1 and etc. participate in the pathogenesis of various cardiac diseases." (PMID 35429991, 2022). "Emerging evidence supports a role for SGK1 and ENaC in promoting fibrosis and adverse hypertrophy in human and murine heart disease." (PMID 28086951, 2017). "Small-molecule inhibitors of SGK1 may be antiarrhythmic in cardiac diseases through attenuation of the abnormally increased late INa." (PMID 37124559, 2023). "Notably, SGK1 is in the rare category of kinases, whose inhibition may be of benefit both in heart disease and cancer." (PMID 28336914, 2017).
neurological disorders (4 papers, 2013 to 2026). "In recent years, a number of scholars have devoted themselves to the study of the role and function of SGK1 in neurological diseases." (PMID 39737082, 2024). "In recent years, some novel SGK1 inhibitors have been discovered and are also being validated for the treatment of neurological disorders." (PMID 39737082, 2024). "In recent years, based on the findings that upregulation of SGK1 may negatively regulate neurological disorders, many scholars have carried out the role of SGK1 inhibition in the treatment of neurological disorders." (PMID 39737082, 2024). "Therefore, in this paper, we briefly review the progress of research on SGK1 in some neurological diseases." (PMID 39737082, 2024). "However, since SGK1 plays a "double-edged sword" role in the development of some diseases, the brain regions and signaling pathways involved in the diseases need to be carefully evaluated if SGK1 is to be used as a drug target for the treatment of neurological diseases." (PMID 39737082, 2024). "Therefore, Clarifying whether SGK1's role in a particular disease is positive or negative will help us further understand and treat neurological diseases through SGK1 as a therapeutic target." (PMID 39737082, 2024).
bacterial infection (2 papers, 2021 to 2022). "Specifically, the downregulated genes are related to neutrophil cell migration (mpx, sgk1), leukocyte recruitment (Irg1l), macrophage chemotaxis to the site of bacterial infection (Cxcr3.2), mucus production (cftr), wound healing, and protection against microbes (il22)." (PMID 34066767, 2021).
movement disorder (2 papers, 2020 to 2024). Neurological conditions resulting in abnormal voluntary or involuntary movement, which may impact the speed, fluency, quality and ease of movement. "In movement disorders, studies have found that there is also a link between SGK1 and α-syn in the skeletal muscle of MPTP-induced PD mouse models, and MPTP caused a decrease of SGK1 expression, which may lead to an increase of α-syn level in muscle." (PMID 39737082, 2024).
brain diseases (1 paper, 2023). "Increased SGK1 expression is an important risk factor for the pathogenesis of several brain diseases." (PMID 37371111, 2023). "SGK1 participates in the regulation of various brain functions and in the pathophysiology of various brain diseases." (PMID 37371111, 2023).
SGK1 also shares sentences with these, for which no sentence is quoted: rheumatoid arthritis (4 papers); gastric adenocarcinoma (3); kidney (3); kidney damage (3); lung adenocarcinoma (3); autism spectrum disorder (2); cervical carcinoma (2); Coronary Heart Disease (2); Crohn disease (2); gastric tumor (2); Glucose intolerance (2); inflammation (2); schizophrenia (2); acute kidney injury (1); acute lung injury (1); acute myeloid leukemia (1); adenoma (1); adenovirus infection (1); adrenocortical tumors (1); atrioventricular block (1); bovine respiratory disease complex (1); brain injuries (1); breast invasive carcinomas (1); breast tumors (1); bronchiectasis (1); Burkitt lymphoma (1); calcification (1); calcium-phosphorus metabolic disorder (1); cardiac arrhythmias (1); cardiomyopathy (1).
A further 58 diseases each share a sentence with SGK1 in 1 paper.